SH3KBP1 (SH3 domain containing kinase binding protein 1)
Description:
Adapter protein involved in regulating diverse signal transduction pathways. Involved in the regulation of endocytosis and lysosomal degradation of ligand-induced receptor tyrosine kinases, including EGFR and MET/hepatocyte growth factor receptor, through an association with CBL and endophilins. The association with CBL, and thus the receptor internalization, may be inhibited by an interaction with PDCD6IP and/or SPRY2. Involved in regulation of ligand-dependent endocytosis of the IgE receptor. Attenuates phosphatidylinositol 3-kinase activity by interaction with its regulatory subunit (By similarity). May be involved in regulation of cell adhesion; promotes the interaction between TTK2B and PDCD6IP. May be involved in the regulation of cellular stress response via the MAPK pathways through its interaction with MAP3K4. Is involved in modulation of tumor necrosis factor mediated apoptosis. Plays a role in the regulation of cell morphology and cytoskeletal organization. Required in the control of cell shape and migration. Has an essential role in the stimulation of B cell activation.
Synonyms: CD2BP3; HSB-1; CIN85; AGMX2; GIG10; HSB1; IMD61; MIG18
Tractability: Antibody: its Gene Ontology location is reachable by antibodies, with high confidence; UniProt places it where antibodies can reach, with medium confidence. PROTAC: UniProt records ubiquitination sites on it; ubiquitination databases record sites on it; its protein half-life has been measured.
Gene: Protein-coding gene on chromosome X (19,533,977 to 19,887,650, reverse strand). Ensembl gene ENSG00000147010.
Subcellular location: Cytoplasm; Cytoplasm, cytoskeleton; Cytoplasmic vesicle membrane; Synapse, synaptosome; Cell junction, focal adhesion
Subcellular location (Human Protein Atlas): Cytosol
Pathways (Reactome):
Disease: InlB-mediated entry of Listeria monocytogenes into host cell; Potential therapeutics for SARS
Signal Transduction: EGFR downregulation; Negative regulation of MET activity
Vesicle-mediated transport: Cargo recognition for clathrin-mediated endocytosis; Clathrin-mediated endocytosis
Developmental Biology: Reelin signalling pathway
Immune System: Antigen activates B Cell Receptor (BCR) leading to generation of second messengers
Gene Ontology:
Molecular function: protein binding; protein-macromolecule adaptor activity; ubiquitin protein ligase binding
Biological process: positive regulation of B cell activation; actin filament organization; cell migration; cell-cell signaling
Cellular component: cytoplasm; cytosol; endocytic vesicle; plasma membrane; cell-cell junction; cytoplasmic vesicle membrane; cytoskeleton; focal adhesion; GABA-ergic synapse; glutamatergic synapse; postsynaptic density; synapse
Gene-disease validity (ClinGen):
ClinGen rates the evidence that SH3KBP1 causes each of these diseases.
immunodeficiency 61 (X-linked): Limited.
Homologues: Orthologues: chimpanzee SH3KBP1 (99% identical), macaque SH3KBP1 (99% identical), dog SH3KBP1 (96% identical), guinea pig SH3KBP1 (96% identical), pig SH3KBP1 (96% identical), rabbit SH3KBP1 (96% identical), mouse Sh3kbp1 (94% identical), rat Sh3kbp1 (94% identical), tropical clawed frog sh3kbp1 (64% identical), zebrafish sh3kbp1 (55% identical), Drosophila melanogaster cindr (28% identical), Caenorhabditis elegans cdap-2 (18% identical). Paralogues in human: CD2AP (37% identical), MNMIP1 (24% identical), NOSTRIN (10% identical).
Diseases named in the same sentence as SH3KBP1 in open-access papers:
SH3KBP1 is named in the same sentence as 49 diseases in open-access papers, as found by Europe PMC text mining. Sharing a sentence is not in itself a finding about the gene and the disease. The quoted sentences say what the papers report.
breast carcinoma (8 papers, 2009 to 2024). "Additional studies in breast cancer demonstrate that hypoglycosylation of MUC1 to form Tn and STn antigens results in increased association with the SH3 domain-containing kinase-binding protein 1, CIN85." (PMID 27483328, 2016).
glioblastoma (3 papers, 2020 to 2024). The most malignant astrocytic tumor (WHO grade IV). "SH3KBP1 was considered promoting glioblastoma tumorigenesis by activating EGFR signaling." (PMID 36193491, 2022). "Besides, SH3KBP1(ranked 10th in patient TCGA-BH-A1FD) was reported to serve as a new regulator of carcinogenic EGFR (Epidermal Growth Factor Receptor), and it could also serve as a potential therapy target for GBM (Glioblastoma multiforme, a kind of cancer) patients with EGFR activation." (PMID 38254011, 2024).
glioma (2 papers, 2020 to 2025). A benign or malignant brain and spinal cord tumor that arises from glial cells (astrocytes, oligodendrocytes, ependymal cells). "Gliomas have high levels of SH3KBP1, and these levels have been linked to glioma patients’ lower survival rates." (PMID 40661938, 2025). "The quantification results indicated a strong positive association between the expression level of SH3KBP1 and glioma grade." (PMID 33643898, 2020). "However, the biological function of SH3KBP1 and its underlying molecular mechanism in regulating glioma tumorigenesis remains largely unknown." (PMID 33643898, 2020). "Glioma cell motility, proliferation, and stem cell self-renewal ability are all markedly reduced when SH3KBP1 is silenced, both in vitro and in vivo when xenograft tumors are growing." (PMID 40661938, 2025). "Based on this background, we focused on investigating the functional roles of SH3KBP1 in glioma tumorigenesis." (PMID 33643898, 2020). "The newly established roles of SH3KBP1 in EGFR-driven tumorigenesis provide a rationale for SH3KBP1 as a novel prognostic marker for patients with glioma and a potential target for further therapeutic investigation." (PMID 33643898, 2020). "Taken together, our study provides clinical and mechanistic evidence demonstrating that SH3KBP1 high expression is essential for EGFR driven tumorigenesis in glioma." (PMID 33643898, 2020). "In this study, we report that both SH3-domain kinase binding protein 1 (SH3KBP1) mRNA and protein levels are highly expressed in GBM and its high expression is associated with worse survival of glioma patients." (PMID 33643898, 2020). "In order to examine the protein levels of SH3KBP1 in vivo, we performed immunohistochemistry (IHC) staining using 27 clinical glioma patients’ specimens, including nine WHO grade II, 10 WHO grade III, eight WHO grade IV." (PMID 33643898, 2020). "EGFR is a well-accepted kinase that plays key roles in glioma cell proliferation and migration and SH3KBP1 activates EGFR signaling." (PMID 33643898, 2020). "Together, these data revealed that the expression level of SH3KBP1 is an indicator of the aggressiveness of malignant gliomas and SH3KBP1 could be used as a biomarker for glioma prognosis." (PMID 33643898, 2020). "To identify the potential biological functions of SH3KBP1 in glioma initiation and progression, we assessed the SH3KBP1expression pattern in different grades of gliomas by using public datasets TCGA and observed that SH3KBP1 expression positively correlates with tumor grades of glioma patients." (PMID 33643898, 2020). "In addition, we performed Kaplan-Meier survival analysis in TCGA data set and the results showed a statistically significant worse prognosis for glioma patients with higher expression of SH3KBP1 compared with lower SH3KBP1 group patients." (PMID 33643898, 2020). "SH3KBP1 was expressed in majority of high-grade gliomas, particularly in GBM specimens." (PMID 33643898, 2020). "It is worth noting that, by comparing the expression of SH3KBP1 in IDH1 wild-type and mutant groups, we observed that SH3KBP1 was highly expressed in wild-type IDH1 tumors, implying that SH3KBP1 may play critical roles in glioma progression." (PMID 33643898, 2020). "Inhibitors or drugs that specifically decrease the expression of SH3KBP1 in glioma cells may be developed to increase the lifespan of glioma patients." (PMID 33643898, 2020). "Thus, we concluded that SH3KBP1 promotes glioma progression dependent on SH3KBP1-EGFR axis." (PMID 33643898, 2020). "Here, we demonstrate that SH3KBP1 interacts physically with EGFR, thereby promoting EGFR activation and glioma tumorigenesis in vitro and in vivo." (PMID 33643898, 2020). "The importance of this high expression is highlighted by the co-expression of SH3KBP1 and SOX2 in glioma clinical samples." (PMID 33643898, 2020). "Thus, we wondered whether SH3KBP1 also plays essential roles in glioma stem cell (GSC)." (PMID 33643898, 2020).
glioma (continued). "We demonstrate that both mRNA and protein levels of SH3KBP1 are highly expressed in GBM (WHO IV) patients than gliomas (WHO II and III) patients and its high expression predicts poor survival of glioma patients." (PMID 33643898, 2020). "In conclusion, our findings reveal a previously unknown signal relay by which SH3KBP1 mediates EGFR activation, thereby enhancing the oncogenic activity of the EGFR signaling pathway in human gliomas." (PMID 33643898, 2020). "Thus, the high expression of SH3KBP1 in GBM may be attributed to SOX10 high expression in GBM and the mechanisms mediating SH3KBP1 overexpression in glioma and GSCs needs further characterized." (PMID 33643898, 2020).
schizophrenia (2 papers, 2020 to 2025). A major psychotic disorder characterized by abnormalities in the perception or expression of reality. "In the rat model study, it was shown that the SH3KBP1 gene was important for the mechanisms of schizophrenia development, which were related to prenatal nutritional deficiency in the mother during pregnancy." (PMID 40416497, 2025). "Analysis of the top 10 genes containing the most differential polymorphisms specifies such genes related to schizophrenia as MUC12 and SH3KBP1." (PMID 40416497, 2025).
viral infections (2 papers, 2024 to 2025). "During the early stages of viral infection, SH3KBP1 recruited TRIM25 and enhanced the K63-linked polyubiquitination of RIG-I, thereby enhancing the expression IFN-β and ISGs." (PMID 39466846, 2024). "In uninfected cells, endogenous SH3KBP1 interacted with TRIM25, and this interaction was significantly enhanced after viral infection." (PMID 39466846, 2024). "In the context of viral infections, the absence of the interaction region between Venezuelan equine encephalitis virus (VEEV) NSP3 and SH3KBP1 in the Alphavirus affects the replication of the virus." (PMID 39466846, 2024).
allergic rhinitis (1 paper, 2014). Inflammation of the nasal mucous membranes caused by an IgE-mediated response to external allergens. "Furthermore, several genes (SH3KBP1, CRNN, FLG, S100A7A) related to allergic inflammation were either induced in allergic rhinitis patients with or without asthma (SH3KB1) or in allergic rhinitis patients only (CRNN, FLG, S100A7A)." (PMID 24475887, 2014).
apraxia (1 paper, 2023). Apraxia is a neurological disorder characterized by the inability to perform tasks or movements, despite having the desire and physical ability to perform them. "Patient 9, a 5-year-old male, presented with delayed and impaired speech and apraxia; a novel duplication was detected, including the SH3KBP1 gene (also called CIN85), which encodes an 85-kDa CBL-interacting protein (CIN85) that facilitates protein-protein interactions." (PMID 37510394, 2023).
centronuclear myopathy (1 paper, 2025). Centronuclear myopathy (CNM) is an inherited neuromuscular disorder characterized by clinical features of a congenital myopathy and centrally placed nuclei on muscle biopsy. "In Dnm2R465W/+ mice, a model for centronuclear myopathy (CNM), depletion of Sh3kbp1 expression aggravates CNM-related atrophic phenotypes and impaired autophagic flux in mutant skeletal muscle fiber." (PMID 40065183, 2025).
HCMV infection (1 paper, 2024). "pUL135 also perturbs EGFR signaling to facilitate HCMV infection, dependent on interactions between pUL135 and binding motifs on ABI1 and SH3-domain kinase-binding protein 1 (SH3KBP1)." (PMID 39354505, 2024).
Insulin resistance (1 paper, 2005). Increased resistance towards insulin, that is, diminished effectiveness of insulin in reducing blood glucose levels. "Because insulin signaling occurs partially through PI-3-kinase, increased expression of Sh3kbp1 by DIO mice may contribute to hepatic insulin resistance via inhibition of PI-3-kinase." (PMID 15985155, 2005).
Intellectual disability (1 paper, 2023). "Loss of function variants in SH3KBP1 are most commonly detected in patients with IMD61, but findings on two families with intellectual disability and large duplications encompassing SH3KBP1, EIF1AX, and RPS6KA3 genes indicate a possible role for SH3KBP1 in addition to that of RPS6KA3." (PMID 37510394, 2023).
upper tract urothelial carcinoma (1 paper, 2020). "The expression level of CNTNAP5 in the kidney is relatively low but still detectable, and only one study reported a SH3KBP1–CNTNAP5 fusion in upper tract urothelial carcinoma." (PMID 32789468, 2020).
cancer (17 papers, 2009 to 2025). A tumor composed of atypical neoplastic, often pleomorphic cells that invade other tissues. "Of these genes, we found Sh3kbp1, Frmd5 and Adrm1 (nos 16–18) to be upregulated in both treatments, and they are described in the literature to be involved in cancer prevention." (PMID 40275631, 2025). "Study demonstrated that SEPT9 competes with the ubiquitin ligase Cb1 for binding to SH3KBP1 and inhibits ubiquitylation of epidermal growth factor receptors in cells which can induce or support the development of cancers." (PMID 33046974, 2020). "In cancer initiation and development, SH3KBP1 has been reported to inhibit Prolyl Hydroxylase 2 (PHD2) binding with Hypoxia-Inducible Factor (HIF) and promotes cancer progression." (PMID 33643898, 2020). "Genes and AS events enrolled in the comprehensive prognostic signature included RHOT1 (ES), SH3KBP1 (AP), AGTRAP (AA), PACS2 (AP), RBPMS (AT), B3GNTL1 (AP), MOBP (AT), NPHP3 (ES), ABCC5 (RI), FKTN (ES) and FKBP8 (AA), many of which are known to play important roles in cancer biology." (PMID 32467664, 2020).
tumor (13 papers, 2013 to 2025). "Mechanistically, CLTB regulated HCC development by activating the NF‐κB–PCLAF axis and stabilized its protein expression through an interaction with SH3KBP1, thereby remodeling the tumor microenvironment." (PMID 40820941, 2025). "CLTB overexpression correlates with poor prognosis, while preclinical models reveal that targeting CLTB or SH3KBP1 synergizes with sorafenib to suppress tumor growth and angiogenesis." (PMID 40820941, 2025). "In patient‐derived xenograft (PDX) models, combined therapy of clathrin inhibitor (chlorpromazine) or SH3KBP1 silencing with sorafenib suppresses tumor growth and reduces microvascular density." (PMID 40820941, 2025). "We then examined anchorage-independent sphere formation and found that compared to the control cells, SH3KBP1 knockdown cells exhibited significantly weaker tumor sphere-tumor formation ability in U251 and U87." (PMID 33643898, 2020). "Xenograft tumor model were further performed to verify this observation and found that SH3KBP1 knockdown significantly inhibited tumor growth and tumor weight in xenograft mouse tumors." (PMID 33643898, 2020). "To further validate SH3KBP1 as a therapeutic target, we assessed whether SH3KBP1 blockade inhibited tumor progression in a subcutaneous PDX mouse model." (PMID 40820941, 2025). "Targeting CLTB or SH3KBP1 synergizes with sorafenib to suppress tumor growth in vivo." (PMID 40820941, 2025). "Our results highlighted the role of SH3KBP1 in tumor immune regulation in HNSC." (PMID 36338975, 2022). "Furthermore, SH3KBP1 was also upregulated in tumor spheres than monolayer cells and plays critical roles in GSCs self-renewal and stemness maintenance." (PMID 33643898, 2020). "SH3KBP1 has been implicated in cell death and shown to mediate down regulation of EGFR, and JUND has been shown to reduce tumor angiogenesis." (PMID 24550933, 2014). "Interestingly, we found that both SH3KBP1 mRNA and protein expression levels were dramatically increased in tumor spheres derived from U251, U87, and LN229 cells than their corresponding monolayer cells, suggesting that SH3KBP1 plays critical roles in regulating GSCs self-renewal." (PMID 33643898, 2020). "AGTRAP1, ABCC5, SH3KBP1, and RBMX were upregulated, while PTGR1 was downregulated in tumor samples as compared to normal samples." (PMID 36338975, 2022). "High expressions of AGTRAP, SH3KBP1, and RBMX were found in tumor tissues and correlated with a poor prognosis." (PMID 36338975, 2022). "To explore the potential functions of SH3KBP1 in GBM progression in vivo, we utilized an intracranially transplanted tumor xenograft model in NOD/SCID mice with U87 cells." (PMID 33643898, 2020).
infection (2 papers, 2024 to 2025). The state of being infected such as from the introduction of a foreign agent such as serum, vaccine, antigenic substance or organism. "Infection with all three PRRSV strains results in reduced levels of endogenous SH3KBP1 protein." (PMID 39466846, 2024).
SH3KBP1 also shares sentences with these, for which no sentence is quoted: colon carcinoma (3 papers); hepatocellular carcinoma (2); osteosarcoma (2); ovarian tumor (2); adenocarcinoma (1); Alzheimer disease (1); antibody deficiency (1); asthma (1); attention deficit-hyperactivity disorder (1); autism (1); B cell lymphomas (1); benign tumors (1); breast adenocarcinoma (1); breast tumors (1); cervical carcinoma (1); colitis (1); colon adenocarcinoma (1); esophageal squamous cell carcinoma (1); genetic disorders (1); invasive breast carcinoma (1); invasive ductal carcinoma (1); leukemia (1); lung carcinoma (1); lymphoma (1); malignant glioma (1); melanoma (1); neurodegenerative disease (1); nutritional deficiency (1); ovarian carcinoma (1); prostate adenocarcinoma (1).
A further 4 diseases each share a sentence with SH3KBP1 in 1 paper.